TNF (tumor necrosis factor)
Diseases named in the same sentence as TNF in open-access papers (continued):
Sharing a sentence is not in itself a finding about the gene and the disease.
cholestasis (63 papers, 2007 to 2025). Impairment of the bile flow caused by obstruction within the liver, or outside the liver in the bile duct system. "According to a prior study, dexamethasone therapy restored the inflammation caused by cholestasis, as evidenced by histological findings and a significant decrease in many inflammatory markers (TNF-α, IL-1β, and IL-6)." (PMID 41517447, 2025). "For example, curcumin, a natural antioxidant in turmeric, plays an important role in the liver damage model caused by cholestasis by reducing the level of the inflammatory factor TNF-α in the liver." (PMID 33062019, 2020). "During cholestasis and liver diseases, macrophages in the liver produce pro‐inflammatory mediators, including TNF, which may explain one of the mechanisms underlying HPS development." (PMID 40344298, 2025). "Levels of IL-6, TNF-α, IL-10, and IL-1β in liver tissue reflect the degree of hepatic inflammation caused by cholestasis, while serum levels of TC, TG, LDL-C, and HDL-C reflect lipid metabolism and oil red O staining visualizes lipid accumulation in liver tissue." (PMID 38523644, 2024). "The deficiency of intestinal SIRT1 exacerbates TNFα-mediated renal damage in mice with cholestasis." (PMID 33513830, 2021). "The decreased NTCP transport activities affect bile acids uptake might be due to increased IL-6 and TNF-α, which could partly explain cholestasis caused by SSd treatment, as noted in our study." (PMID 30034340, 2018). "In the presence of preexisting liver dysfunction induced by cholestasis, serum TNF‐α was eight times higher than that in rats with normal liver function after receiving Escherichia coli, despite showing equivalent circulating endotoxin levels." (PMID 40344298, 2025). "Further studies have shown that the development of cholestasis in response to LPS treatment is largely due to increased production of inflammatory cytokines, particularly IL-1β and tumour necrosis factor-α (TNF-α)." (PMID 39680527, 2024). "In this regard, dysregulation of the localization, protein levels and transcript expression of proteins in bile salt transport are essential mechanisms by which LPS and inflammatory cytokines such as TNF-α and IL-1β lead to the development of cholestasis." (PMID 39680527, 2024). "Among them, TNF-α, IL-6, and IL-10 play important roles in inflammatory responses of the lungs after cholestasis." (PMID 39744639, 2024). "Part of the explanation for the raised serum concentration of IL-1ß in this disease is the activation of Kupffer cells by IL-17 (released by T helper cells and neutrophils during cholestasis), which leads to the induction of TNFα and IL-1ß." (PMID 37175814, 2023). "Inflammation in NASH and cholestasis is characterized not only by enhanced levels of IL-1ß but also by increased release of IL-6 and TNFα." (PMID 37175814, 2023). "Altered expression of CR-dependent regulatory genes during PNAC accompanies cholestasis and is, in part, due to increased cytokine (IL-1β and TNFα) production." (PMID 37647292, 2023). "It was demonstrated that ANIT-induced cholestasis increased the levels of IL-1β, IL-6, and TNF-α and decreased the levels of IL-10." (PMID 36409145, 2022). "Cholestasis can trigger the release of cytokines such as IL-6, IL-1β, and TNF-α, which, in turn, repress NTCP transcription." (PMID 35495620, 2022). "IL-1β, IL-6, TNF-α, and IL-10 are common indices used to assess the inflammatory response, oxidative stress, and apoptosis, among others, in cholestasis." (PMID 36409145, 2022). "The expression levels of serum inflammatory cytokines, such as tumor necrosis factor-α (TNF-α), interleukin (IL)-1β, and IL-6, are increased in patients with cholestasis, demonstrating that inflammation plays a role in cholestasis." (PMID 35924060, 2022).
cholestasis (continued). "Our group has previously defined critical roles for the ADAM17-regulated cytokines TNFα and IL-6, cytokine receptor TNFRI, and immune cell adhesion molecule VCAM-1, in cholestasis associated sickness behavior development in BDL mice." (PMID 35095853, 2021). "In the present study, cholestasis-induced inflammation in rats undergoing bile duct ligation was shown by the significant increase in serum levels of TNF-α, NF-ĸB and IL-6 pro-inflammatory cytokines compared to the control group." (PMID 34567144, 2021). "Increased circulating TNFα levels have been documented in both patients with cholestatic liver diseases, and in animal models of cholestasis." (PMID 35095853, 2021). "Various pro-inflammatory cytokines such as TNF-α and IL-6, which are activated in cholestasis, are responsible for this regulation." (PMID 34567144, 2021). "Co-incubation of TNFα and Actinomycin D determines cholangiocyte apoptosis and loss of secretion capabilities in BDL rat, suggesting that during cholestasis reactive cholangiocytes are more susceptible to TNFα cytotoxic effect." (PMID 30275402, 2018). "The results in our experimental model showing that TNFα expression was significantly increased in GWI-treated animals as compared to unexposed ones after BDL-induced cholestasis are in line with findings in human studies." (PMID 30177688, 2018). "Pro-inflammatory cytokines such as TNF-α and IL-6 are mainly involved in cholestasis and the synthesis of acute-phase proteins." (PMID 26343741, 2015). "Accordingly, blocking the action of IL-1β or TNF-α with an antibody directed against the IL-1β receptor or a TNF-α inactivating fusion protein results in a reduction of LPS-induced cholestasis, which was almost completely abolished by combined inactivation of IL-1β and TNF-α." (PMID 39680527, 2024). "However, the fact that cholestasis induced by an LPS-induced inflammatory response can only be attenuated by the combined administration of antagonistic antibodies against both TNF-α as well as IL-1β suggests that IL-1β has a relevant role in this context." (PMID 39680527, 2024). "The disruption of the blood supply to liver cells as a consequence of cholestasis significantly contributes to the inhibition of the activity of protein biliary transporters, which may be reflected in elevated levels of TNF-α, IL-1β (interleukin-1β), and IL-6." (PMID 37834802, 2023). "Our previous study suggested that TNF signaling pathway may be the important mechanism for SHCZF against cholestasis." (PMID 35196362, 2022). "Moreover, Q7R can also reduce TNF-α, IL-1β, PTGS1, PTGS2, NCOA2, and NF-κB levels and alleviate the inflammatory response caused by cholestasis." (PMID 36699093, 2022). "In cholestasis, TNFα mediates IL-6 release from macrophages to aggravate renal dysfunction." (PMID 34831270, 2021). "Similarly, CAR activation by TCPOBOP reduced cholestasis-induced liver dysfunction, inflammation (p65 nuclear translocation, mRNA expression of TNFα, IL-1β, IL-6) and oxidative stress." (PMID 34502180, 2021). "In support of this hypothesis, treatment with dexamethasone counteracted cholestasis-related hepatic inflammation by preventing NFκB translocation to the nucleus and restored TNFα, IL-6, and IL-1β mRNA levels in the liver of cholestatic rats." (PMID 33198224, 2020). "In addition, excessive production of TNF-α and IL-6 also leads to a decrease in bile flow, which further leads to cholestasis." (PMID 31827690, 2019). "The most plausible is that cholestasis induces the release of BA-induced pro-inflammatory cytokines (TNF-α, chemokine CCL2, chemokine C-X-C motif ligand 2, and CXCL2, among others) by hepatocytes in addition to the responses of cholangiocytes and the innate immune cells in liver." (PMID 31546715, 2019).
cholestasis (continued). "On the other hand, PE resveratrol and ginsenosides have been surprisingly reported as anti-cholestatic agents in the EE murine model, evidenced by reduced levels of biochemical markers of cholestasis, oxidative stress, as well as of the pro-inflammatory cytokines TNF-α, IL-6, and IL-1β." (PMID 31546715, 2019). "Besides, the pro-inflammatory cytokines differently regulate hepatic transporters depending on the mechanism of cholestasis; indeed, TNF-α and IL-1β downregulate the bile salt export pump (BSEP) and decrease BAs secretion." (PMID 31546715, 2019). "For example, TNF-α and IL-1β play important roles in cholestasis-induced cell death and fibrosis." (PMID 27872855, 2016). "TRAF1 regulates CD40 and TNF transduction signaling and may play a role in cholestasis-induced sick behaviours mediated by TNFα." (PMID 23710202, 2013). "Proinflammatory cytokines, such as TNF-α, and IL-1 beta enhance liver damage in cholestasis." (PMID 18045488, 2007). "Although the 2 transcriptomes mostly exhibited distinct expression changes, there were common changes in both TNF-α signaling and complement pathway genes, suggesting some similarities with respect to inflammation (and similarities with pathways known to be dysregulated in cholestasis )." (PMID 37490339, 2023). "For example, TNF-α can inhibit the transcription of the tubule bile acid transporter Abcb11, bilirubin outlet Abcc2, and sterol transporter Abcg5/8 in intestinal inflammation, cholestasis, or the activation of hepatic macrophages, and thus affect the expression of transporters." (PMID 35163972, 2022). "In cholestasis, downregulation of AQP8 by TNF-α after LPS stimulation reduces water permeability in hepatocytes, impairing bile formation and exacerbating cholestasis." (PMID 39544938, 2024). "Cytokines, namely interleukin-1 (IL-1), IL-6 and tumor necrosis factor alpha (TNF-α) lead to disruption of hepatobiliary transport systems and thus result in cholestasis." (PMID 25858884, 2015). "In our study, the levels of proinflammatory cytokines (TNF-α and IL-6) were decreased by MRS treatment, suggesting that MRS may attenuate liver injury in cholestasis via the reduced inflammatory response and macrophage infiltration." (PMID 31827690, 2019). "During the tumorigenesis of cholangiocarcinoma, cholestasis and chronic inflammation may induce bile duct epithelial cells to produce variable cytokines including IL-6, IL-8, TGF-β1, TNF-α, platelet-derived growth factor, and epidermal growth factor." (PMID 30469416, 2018). "However, in advanced cholestasis, RIO treatment resulted in a significant decrease of TNFα mRNA and tended to reduce MCP1 expression, while VCAM and IL1β remained unchanged." (PMID 29921982, 2018). "Histological findings and a significant drop in several markers of inflammation (p65 nuclear translocation, mRNA expressions of TNF-α, IL-1β, IL-6) showed that DEX treatment reversed cholestasis-induced inflammation, and similar results have been obtained with oxidative stress markers." (PMID 30252871, 2018). "Serum values of TNFα and sTNF-R1 were available in 20 patients with cholestasis and 31 patients without cholestasis." (PMID 22035247, 2011). "Additionally, TNFα was demonstrated to increase the release of ALR in an in vitro model and therefore might contribute to low cellular levels in NASH and cholestasis." (PMID 37175814, 2023). "Similarly, the levels of TC, TBA, γ-GT, TBIL, the expression of TNF-α, TIMP-1, and the BAX/BCL-2 ratio were significantly increased in cholestasis-induced rats compared with the control rats, and these changes were effectively alleviated following treatment with ZYP." (PMID 34539394, 2021).
leukocytosis (63 papers, 2012 to 2026). "Changes in sleep patterns can cause leukocytosis and an increase in natural killer cells, as well as an increase in inflammatory cytokine production, such as TNF and IL6." (PMID 37663979, 2023). "High levels of tumor necrosis factor-alpha are linked to leukocytosis, high blast counts, and worse survival in patients with acute leukemia." (PMID 35547942, 2022). "In clinical trials, multiple injections of the drug with concomitant radio- and chemotherapy caused leukocytosis due to neutrophils and a significant increase in tumor necrosis factor (TNF)." (PMID 33959120, 2021). "Markers of chronic inflammation, such as TNF-α and leukocytosis, are all associated with aging and age-related diseases." (PMID 28977399, 2017). "TNF-alpha produced by squamous cell carcinomas has been implicated to have a pathogenic role in the paraneoplastic effects of leukocytosis." (PMID 27866514, 2016). "Even though inflammation starts as a local reaction, it associates a systemic acute phase response that involves pro-inflammatory mediators (IL-6; IL-1β; TNF-α), bone marrow response causing leukocytosis, liver response with acute phase proteins (APPs) synthesis." (PMID 31664997, 2019). "Moreover, we determined the association between leukocytosis in mothers’ blood before and during labor and TNF-α in umbilical cord blood (p=0.02 and 0.007, respectively)." (PMID 24161005, 2013). "Abdominal adipose tissue secretes a variety of inflammatory factors, such as tumor necrosis factor and interleukin-6, which can stimulate the immune system and lead to leukocytosis." (PMID 40115939, 2025). "Clinical and translational studies have shown that HU therapy not only reduces leukocytosis but also downregulates inflammatory cytokines such as TNF-α, IL-8, and soluble adhesion molecules, thereby lowering neutrophil activation and vascular adhesion." (PMID 41282081, 2025). "Interleukin-1 and tumor necrosis factor (TNF) can induce IL-6 expression, which stimulates hematopoiesis, creating a consistent contribution to the leukocytosis that can accompany ACS." (PMID 39274304, 2024). "IL-6, a pyrogen similar to IL-1 and TNF-α, mediated the acute phase response characterized by leukocytosis and increased acute phase reactants." (PMID 37628768, 2023). "Previous studies have shown that acute short-term exercise can trigger a pro-inflammatory effect presented by elevated secretion of IL-6 and CRP, and to a lesser extent, TNF-α levels, in addition to triggering leukocytosis and oxidative stress." (PMID 36504710, 2022). "In clinical trials, multiple injections of the drug with concurrent radio- and chemotherapy resulted in neutrophil-induced leukocytosis and a significant increase in tumor-necrosis-factor (TNF) levels." (PMID 36237313, 2022). "Another group of factors intensifying exercise leukocytosis is secreted cytokines (TNF, IL-1, IL-6)." (PMID 33802129, 2021). "In male subjects with high blood Pb and Pb-exposed workers, the inflammatory response has been manifested by leukocytosis and increased inflammatory mediators, including TNF-α." (PMID 31771282, 2019). "Accordingly, male subjects with high blood Pb showed leukocytosis and increased tumor necrosis factor (TNF)-α levels." (PMID 31694300, 2019). "The inflammatory response elicited by Pb has been reported in male subjects with high blood Pb who showed leukocytosis and increased TNF-α, and in Pb-exposed workers where inflammatory mediators were increased with increased blood Pb levels." (PMID 31694300, 2019). "CPB induced leukocytosis with increased plasma levels of tumor necrosis factor-α and interleukin-6 indicating a potent inflammatory response." (PMID 29593559, 2018). "Both TNF-α and IL-6 have been shown to decrease with long-term physical activity resulting in significant decreases in leukocytosis and neutrophilia." (PMID 22363616, 2012).
leukocytosis (continued). "For instance, whereas tumor necrosis factor (TNF-α) and interleukin-1 (IL-1) generate fever, interleukin-8 (IL-8) and colony-stimulating factors cause chemotaxis and neutrophil maturation, which results in leukocytosis." (PMID 39727640, 2024). "The mechanisms of clozapine-induced leukocytosis may be related to changes in plasma concentrations of the granulocyte colony-stimulating factor, tumor necrosis factor-α, interleukin (IL)-2 cytokines, and IL-6 cytokines." (PMID 36922799, 2023). "Leukocytosis following exercise is a well-described stress/inflammatory activation phenomenon in healthy humans: our data showed that leukocytosis after triathlon competition was coincident with the increase of the inflammatory cytokines TNF-α and IL-6." (PMID 32256948, 2020). "The exercise-dependent systemic inflammatory response that we observed immediately after a soccer game encompassed both strenuous physical activity–induced transient leukocytosis as well as increases in circulating IL-6 and TNF α, early mediators of exercise-induced inflammation." (PMID 32879387, 2020). "Neutrophilia with moderate leukocytosis observed in this study after mixture administration could be the result of neutrophil release and mobilization under inflammatory IL-6 and TNF-α from marginal neutrophil pools." (PMID 30669347, 2019). "Oral glycine and Pro‐Hyp attenuated the recruitment of inflammatory cells into the colonic tissue, possibly owning to their prevention of leukocytosis and lymphocytosis, and this may explain their effectiveness in suppressing the colonic increase in IL‐6 and TNF‐α." (PMID 29983966, 2018). "In addition, some patients displayed marked leukocytosis and IL-6 and TNF-α production in plasma." (PMID 28379166, 2017). "However, cancer has been shown to produce myeloid growth factors, such as granulocyte colony-stimulating factor, tumor necrosis factor-alpha, interleukin-1, and interleukin-6, which may influence tumor-related leukocytosis and neutrophilia." (PMID 24089602, 2013). "The rAcH3.3 instillation also increased apoptotic activity (cleavage of caspase 3 and 9) and triggered acute systemic inflammatory marker activation (TNF-α, IL-6, MCP-3, or CXCL-1) in plasma, accompanied by leukocytosis and lymphocytosis." (PMID 37759735, 2023). "Therefore, the tendency of TNFα to increase may be a compensatory reaction due to leukocytosis." (PMID 36983819, 2023). "Because sympathetic nervous activation causes 2-adrenergic receptor-mediated leukocytosis and CPAP reduces catecholamine levels and sympathetic nerve activation, the monocytes gained before and after CPAP may represent distinct populations, illustrating the decrease in TNF-α production." (PMID 36952521, 2023). "One LD50 injection in mice produced a severe envenomation state, with a significant reduction of the complement activity, leukocytosis, neutrophilia, monocytosis, and strong systemic production of IL-6, CCL2, and TNF-α." (PMID 33936074, 2021). "LPS-induced rats showed significant leukocytosis, and elevated serum levels of CRP, TNF-α, IL-1β, IL-6, IL-8, MCP-1, malondialdehyde (MDA) and 8-hydroxy-2′-deoxyguanosine (8-OHdG), accompanied with diminished antioxidants." (PMID 30858869, 2019). "Leukocytosis is common in patients with SCD and manifests itself by elevated monocyte and neutrophil counts and high circulating levels of inflammatory cytokines like TNF-α, IL-1, and IL-828." (PMID 40169559, 2025). "In a previous study, patients with COPD included higher proportions of smokers with elevated CRP, leukocytosis, interleukin (IL)-6, and tumor necrosis factor (TNF)-α levels when compared to patients without COPD." (PMID 34537026, 2021). "In addition to amelioration of leukocytosis, SBH reduced the circulating levels of inflammatory mediators, including CRP, MCP-1, TNF-α, IL-1β and IL-6 in LPS-induced rats." (PMID 30858869, 2019).